BCAT1 (branched chain amino acid transaminase 1)
Description:
Catalyzes the first reaction in the catabolism of the essential branched chain amino acids leucine, isoleucine, and valine.
Synonyms: BCT1; ECA39; BCATc; MECA39; PNAS121; PP18
Tractability: Small molecule: a structure with a bound ligand is known; a high-quality ligand is known; it has a high-quality binding pocket; it belongs to a druggable protein family. PROTAC: ubiquitination databases record sites on it; its protein half-life has been measured; a small molecule that binds it is known.
Target class: Enzyme; Transferase
Chemical probes: BAY-069 (high quality)
Gene: Protein-coding gene on chromosome 12 (24,810,024 to 24,949,556, reverse strand). Ensembl gene ENSG00000060982.
Subcellular location: Cytoplasm
Pathways (Reactome):
Metabolism: Branched-chain amino acid catabolism
Gene Ontology:
Molecular function: branched-chain-amino-acid transaminase activity; L-isoleucine-2-oxoglutarate transaminase activity; L-leucine-2-oxoglutarate transaminase activity; L-valine-2-oxoglutarate transaminase activity; catalytic activity
Biological process: branched-chain amino acid biosynthetic process; G1/S transition of mitotic cell cycle; L-isoleucine catabolic process; L-valine catabolic process; branched-chain amino acid metabolic process; L-leucine catabolic process
Cellular component: cytoplasm; cytosol; mitochondrion
Genetic constraint (gnomAD): Loss-of-function variants: 46 observed, 48.26 expected, observed/expected ratio (o/e) 0.95, 90% interval 0.75 to 1.22. The upper end of that interval is the gene's LOEUF score, 1.22, which puts it in group 5 of 6, group 1 being the genes least tolerant of losing a copy. Missense variants: 430 observed, 457.33 expected, observed/expected ratio (o/e) 0.94, 90% interval 0.87 to 1.02. Synonymous variants: 163 observed, 161.63 expected, observed/expected ratio (o/e) 1.01, 90% interval 0.89 to 1.15.
Homologues: Orthologues: chimpanzee BCAT1 (99% identical), macaque BCAT1 (97% identical), dog BCAT1 (94% identical), rabbit BCAT1 (88% identical), pig BCAT1 (85% identical), mouse Bcat1 (85% identical), guinea pig BCAT1 (84% identical), rat Bcat1 (76% identical), tropical clawed frog bcat1 (69% identical), zebrafish bcat1 (68% identical), Caenorhabditis elegans bcat-1 (51% identical), Drosophila melanogaster Bcat (51% identical), and 1 more. Paralogues in human: BCAT2 (56% identical).
Diseases named in the same sentence as BCAT1 in open-access papers:
BCAT1 is named in the same sentence as 147 diseases in open-access papers, as found by Europe PMC text mining. Sharing a sentence is not in itself a finding about the gene and the disease. The quoted sentences say what the papers report.
glioma (63 papers, 2015 to 2025). A benign or malignant brain and spinal cord tumor that arises from glial cells (astrocytes, oligodendrocytes, ependymal cells). "In numerous tumors, including bladder cancer, melanoma, and glioma, enhanced expression of BCAT1 is associated with tumor progression and patient prognosis." (PMID 40274762, 2025). "Nonetheless, the association of BCAT1 with adaptive response to temozolomide in glioma remains to be elucidated." (PMID 39075053, 2024). "Enhanced BCAT1 expression correlates with aggressive characteristics in various cancers, including glioma, where it associates with unfavorable patient prognosis." (PMID 39075053, 2024). "BCAT1 expression is silent in IDH mutation glioma due to extensive DNA hypermethylation within the promoter region of BCAT1." (PMID 37298317, 2023). "Previously, several studies have revealed the risk role of high expression of BCAT1 in the prognosis of patients with glioma, prostate cancer, urothelial cancer, and HNSCC." (PMID 34984849, 2022). "Transcriptional studies revealed that in glioblastoma tumors, classified according to the isocitrate dehydrogenase (IDH) mutation status, BCAT1 expression was significantly higher in IDHwt gliomas while in IDHmut gliomas it was suppressed." (PMID 35409380, 2022). "we explored the association between BCAT1 and apoptosis, hypoxia and angiogenesis metagenes, BCAT1 expression was positively related with apoptosis, hypoxia and angiogenesis processes in gliomas especially in GBM." (PMID 33493139, 2021). "BCAT1 levels have been positively associated with tumour progression and an unfavourable prognosis in many malignancies, including gastric cancer, glioma, hepatic cancer, and nasopharyngeal carcinoma." (PMID 32571264, 2020). "The aberrant DNA methylation in BCAT1 promotor region was associated with in colorectal cancer, ovarian cancer and gliomas." (PMID 31226958, 2019). "Low BCAT1 mRNA expression levels in IDH1MUT glioma were associated with BCAT1 promoter hypermethylation." (PMID 28467784, 2017). "For instance, the reduction of Glu levels resulting from the decreased activity of the branched–chain amino acid transaminase 1 (BCAT1) enzyme has been suggested to be strongly associated with the pathogenesis of the IDH1 mutated gliomas." (PMID 26820720, 2016). "Reduced expression of branched‐chain amino acid transferase 1 (BCAT1) in IDH1‐mutated gliomas has been shown, in part, to be caused by hypermethylation of the BCAT1 promoter region." (PMID 25864878, 2015). "Importantly, a high-quality study linked metabolism and tumors, where it found that gliomas expressed high levels of branched chain amino-acid transaminase 1 (BCAT1)." (PMID 34805164, 2021). "Furthermore, BCAT1 was associated with muscle wasting in gliomas." (PMID 36119495, 2022). "However, the associated molecular mechanisms of BCAT1 in glioma remain poorly understood, and thus more extensive research in this area could provide insight towards improved diagnosis and treatment." (PMID 33493139, 2021). "Through the CHIP/BCAT1 axis, it enhances glioma sensitivity to temozolomide by reducing glutathione (GSH) synthesis and increasing oxidative stress." (PMID 40438606, 2025). "Low-grade gliomas and secondary glioblastomas lead to excessive production of (R)-2HG, which can effectively inhibit 2OG-dependent transaminases BCAT1 and BCAT2." (PMID 40438606, 2025). "Clinically, we reveal a positive correlation between SIRT5 and BCAT1 levels in glioma samples, with higher expression levels predicting more advanced glioma grades and poorer clinical outcomes." (PMID 40195331, 2025). "In gliomas, lincRNA00963 reduces the expression level of miR-506, thereby affecting the downstream target protein branched-chain Amino Acid Transaminase 1 (BCAT1) and weakening the inhibitory effect of miR-506 on tumors." (PMID 40248198, 2025).
glioma (continued). "Critically, we also demonstrate that the CHIP/BCAT1 axis enhances temozolomide sensitivity in glioma cells by reducing GSH synthesis and increasing oxidative stress." (PMID 39075053, 2024). "Our investigation unveils that in comparison to microglial cells, glioma cells exhibit lower levels of BCAT1 ubiquitination, leading to an extended half-life." (PMID 39075053, 2024). "In summary, our study elucidates the regulatory mechanisms of BCAT1 ubiquitination and degradation in glioma." (PMID 39075053, 2024). "Critically, BCAT knockdown decreases IC50 values of temozolomide in glioma cells and BCAT1 overexpression confers resistance to temozolomide." (PMID 39075053, 2024). "In this study, we reveal that ubiquitination at Lys360 facilitates BCAT1 degradation, with low ubiquitination levels contributing to high BCAT1 expression in glioma cells." (PMID 39075053, 2024). "CHIP-mediated BCAT1 degradation via the proteasomal pathway inhibits glioma cell proliferation and tumor formation both in vitro and in vivo." (PMID 39075053, 2024). "In contrast, in acute myeloid leukemia, glioma, and lung cancer, massive expression of BCAT1 reduces the level of its substrate α-KG and promotes tumor progression." (PMID 39324007, 2024). "We demonstrate that CHIP-mediated BCAT1 degradation inhibits glioma cell proliferation and enhances temozolomide sensitivity, thereby providing a potential therapeutic target for developing anti-tumor drugs." (PMID 39075053, 2024). "Since the role of BCAT1 overexpression in glioma development was reported in 2013, BCAT1 has received increasing attention as a prognostic tumour marker and an attractive target for cancer therapy in many types of tumours." (PMID 38369471, 2024). "Survival analysis indicated that glioma patients exhibiting high BCAT1 expression and low CHIP expression had shorter overall survival compared to those with low BCAT1 expression and high CHIP expression." (PMID 39075053, 2024). "In this study, we discover that ubiquitination at Lys360 facilitates BCAT1 degradation, and low ubiquitination levels contribute to high BCAT1 expression in glioma cells." (PMID 39075053, 2024). "A high level of BCAT1 expression was identified in gliomas and leukemia with wild-type IDH, and mimics the mutant IDH phenotype in which aberrant production of 2-hydroxyglutarate competitively inhibits αKG function." (PMID 39255038, 2024). "Subsequently, xenograft assay was conducted to assess the translational significance of the CHIP/BCAT1 axis in glioma treatment." (PMID 39075053, 2024). "McBrayer found that in IDH mutant gliomas, the expression of the BCAT1 was significantly inhibited due to 2-HG-mediated hypermethylation that resulted in a significant decrease in the production of intracellular glutamate from BCAAs." (PMID 37298317, 2023). "In CGGA (Chinese Glioma Genome Atlas), a significant positive correlation was found between LDHA and BCAT1 expression in both primary and recurrent gliomas, and a similar positive correlation was observed in gliomas at all malignant levels." (PMID 37298317, 2023). "Branched-chain amino acid transaminase 1 (BCAT1) activity is silenced by epigenetic methylation in IDH mutant gliomas." (PMID 37298317, 2023). "While BCAT1 increases intracellular glutamate levels, promoting glioma proliferation, GLUL converts glutamate to glutamine, decreasing cytosolic glutamate levels." (PMID 36831869, 2023). "Other studies have found that BCAT1 expression was associated with aggressiveness and poor prognosis in IDH1 wild-type gliomas using MR imaging features." (PMID 36119495, 2022). "Inhibition of BCAT1 resulted in a decreased efflux of glutamate and brought about the impaired invasiveness of glioma cells." (PMID 36295820, 2022). "In human gliomas carrying wild-type isocitrate dehydrogenase-1, BCAT1 promotes cell proliferation through amino acid catabolism." (PMID 35562710, 2022).
glioma (continued). "Among these proteins, we identified Disintegrin and metalloproteinase domain-containing protein 17 (Adam17), known to promotes glioma cell malignant phenotype and Branched-chain-amino-acid aminotransferase (Bcat1) which promotes cell proliferation in glioma." (PMID 33402730, 2022). "Previously identified vulnerabilities such as upregulation of BCAT1 in IDH wildtype glioma were also identified in our study." (PMID 35526077, 2022). "Several known glioma markers were identified through this analysis such as Vimentin, Nestin, BCAT1, and S100A1." (PMID 35526077, 2022). "BCAT1 has been identified as being highly expressed in a variety of cancers, such as gliomas, gastric cancer, and hepatocellular carcinoma, and has been frequently reported as a promoter in the occurrence and development of these cancers." (PMID 34984849, 2022). "To evaluate the relationship between BCAT1 and glycolysis in gliomas, we firstly performed the Pearson correlation analysis using both TCGA and CGGA datasets." (PMID 33493139, 2021). "In the present study, we accessed glioma patient cohorts and tissue microarray to evaluate the expression pattern of BCAT1 for determining its prognostic value and its relationship with IDH1 mutation status." (PMID 33493139, 2021). "We concluded that BCAT1 is a strong prognostic factor for glioma patients and involved in the malignant progression of IDH1 wild-type gliomas." (PMID 33493139, 2021). "Branched-chain amino acid transaminase 1 (BCAT1), which is located in the cytosol and widely expressed in the brain, is present at significantly lower levels in mutIDH1R132H glioma PTB and PDX compared with WT IDH1 glioma samples." (PMID 35028610, 2021). "Nonetheless, as a promising target in primary glioblastoma, comprehensive reports on the relationship between BCAT1 gene expression and clinical outcome or molecular features in glioma are still required." (PMID 33493139, 2021). "In this study, we evaluated the expression of BCAT1 in gliomas and its potential involvement in tumor biological processes." (PMID 33493139, 2021). "Based on the large-scale sample collection, we analyzed the gene expression pattern of BCAT1 in glioma tissues as well as its relationship with IDH1 status and other clinical features." (PMID 33493139, 2021). "To conclude, our work highlights that high expression of BCAT1 is a sensitive marker for predicting poor prognosis of IDH1 wild-type glioma patients." (PMID 33493139, 2021). "Overall, these data suggest BCAT1 is correlated with the immunosuppressive signature of IDH1 wild-type gliomas." (PMID 33493139, 2021). "From our results, BCAT1 is higher expressed in glioblastoma than in lower grade gliomas and higher in astrocytoma than in oligodendroglioma as well as higher in classical and mesenchymal subtypes than in proneural subtype glioblastoma." (PMID 33493139, 2021). "For glioma, it is indicated that loss of BCAT1 is a sensitive marker for IDH-mutant diffuse gliomas and that decreased expression of BCAT1 correlates with improved patient survival in IDH wild-type gliomas." (PMID 33493139, 2021). "As shown in functional heatmap analyses, glioma-derived BCAT1 expression was positively correlated with biomarker gene expression of apoptosis, hypoxia and angiogenesis in both the TCGA and CGGA datasets." (PMID 33493139, 2021). "Increased levels of the BCAT gene, BCAT1 have been extensively reported in malignancies including gliomas, ovarian, colorectal, gastric cancer, nasopharyngeal carcinomas, breast cancer and chronic myeloid leukemia (CML)." (PMID 33367952, 2021). "Meanwhile, high expression of BCAT1 is also linked with a high percentage of M2 and Treg cell infiltration, which are more frequently occurring in IDH wild-type gliomas." (PMID 33493139, 2021).
glioma (continued). "Suppression of BCAT1 in glioma cell lines blocked the excretion of glutamate and led to reduced proliferation and invasiveness in vitro, as well as significant decreases in tumor growth in a glioblastoma xenograft model." (PMID 33493139, 2021). "To evaluate the general expression pattern of BCAT1 in gliomas, we compared the mRNA and protein levels of BCAT1 between different tumors, grades, histological and molecular subtypes through several online databases." (PMID 33493139, 2021). "The Human Protein Atlas and TCGA databases also confirmed that gliomas own a high expression of BCAT1 among pan-cancers." (PMID 33493139, 2021). "The results showed that BCAT1 synergized well with other immune checkpoint molecules in gliomas, which were observed in both TCGA and CGGA datasets." (PMID 33493139, 2021). "Another study has suggested that BCAT1 mainly promotes tumour proliferation by contributing to amino acid metabolism in glioma." (PMID 32571264, 2020). "In the top 5 of differentially expressed genes were LDHA and BCAT1, genes that are known to be hypermethylated in low grade, IDHmut gliomas." (PMID 31747973, 2019). "Branched-chain amino acid transaminase 1 (BCAT1), an enzyme that initiates the catabolism of branched-chain amino acids and therefore raises the level of intracellular glutamate, promotes glioma proliferation in vitro and in vivo." (PMID 30716120, 2019). "For example, IDH-wild-type glioma cells routinely express the enzyme branched-chain amino acid transferase-1 (BCAT1) that converts α-KG to glutamate." (PMID 28074274, 2017). "When BCAT1 is knocked down with shRNA, glioma cell growth is reduced in vitro and in vivo, and when treated with gabapentin, a pharmacological inhibitor of BCAT1, glutamate release is also attenuated." (PMID 28491867, 2017). "In IDH1MUT glioma, we observed strikingly higher expression levels of GLUD1/2 than in IDH1WT glioma, whereas BCAT1/2 expression levels were much lower in IDH1MUT gliomas than in IDH1WT glioma, as has been reported previously." (PMID 28467784, 2017). "Another study reported that the expression of BCAT1 was significantly reduced in IDH1 MT glioma cells compared with their wild-type counterparts, and it was investigated by hyperpolarized 13C magnetic resonance spectroscopy (MRS)." (PMID 27626306, 2016). "Recent study has demonstrated a link between IDH1 function and BCAT1 expression in gliomas, as BCAT1 was shown to be involved in tumor growth and disease progression only in gliomas with wild-type (non-mutated) IDH1." (PMID 26372729, 2015). "The implication of aberrant DNA methylation in the control of BCAT1 expression in cancer has been also demonstrated in gliomas and colorectal cancer." (PMID 26372729, 2015). "Although previous studies have reported SLC7A11 (xCT) and BCAT1 as potential biomarkers for glioma-associated seizures, our dataset did not reveal significant mutation frequencies in these genes." (PMID 40718831, 2025). "Additionally, low CHIP expression correlates with high BCAT1 expression and poor prognosis in glioma patients." (PMID 39075053, 2024). "Collectively, our study reveals a previously unknown regulatory mechanism of BCAT1 post-translational modification in glioma and offers a potential therapeutic target to enhance temozolomide sensitivity." (PMID 39075053, 2024). "Gabapentin reduces glutamate synthesis through inhibition of BCAT-1 and, through the inhibition of thrombospondin-1 receptor α2δ-1, has been found recently to reduce functional connectivity of glioma and neuronal networks by inhibiting synaptogenesis and thus reducing tumor cell proliferation." (PMID 38225589, 2024). "Moreover, CHIP-mediated BCAT1 degradation induces metabolic reprogramming, and impedes glioma cell proliferation and tumor growth both in vitro and in vivo." (PMID 39075053, 2024). "Importantly, CHIP inhibits the proliferation of glioma cells both in vitro and in vivo, which is rescued by ectopic expression of BCAT1." (PMID 39075053, 2024).